USP10 (ubiquitin specific peptidase 10)
Diseases named in the same sentence as USP10 in open-access papers (continued):
Sharing a sentence is not in itself a finding about the gene and the disease.
tumor (continued). "Not only does USP10 control tumour intrinsic pathways and biological processes regulated by WNT, loss of USP10 suppressed cell death of non-transformed cells exposed to cultured medium from tumour organoids." (PMID 39443725, 2024). "USP10 is crucial in the tumorigenic signalling of β-Catenin and its abundance strongly enhanced WNT target gene expression and is required to maintain a stemness-like expression profile, in CRC and murine tumour organoids, respectively." (PMID 39443725, 2024). "Similar effects were observed in animal experiments, which showed smaller subcutaneous tumor sizes in the USP10 knockdown groups than in the USP10 negative control group." (PMID 39430239, 2024). "Furthermore, our experiments showed that the USP10-GSK3β-ULK1 axis was involved in autophagy and tumor progression in OS." (PMID 39218913, 2024). "Our results demonstrated that neither USP10 overexpression nor USP10 knockdown exhibited significant differences in tumor growth in the 4T1 xenograft mouse model." (PMID 39206932, 2024). "Furthermore, mice bearing USP10-depleted LN229 and GBM2 cells had a delayed tumor formation compared with relevant control, and these alterations were reversed by RUNX1 overexpression." (PMID 36949071, 2023). "Bioluminescence images revealed that significant differences in tumor volume between U251 and GBM1 cells overexpressed USP10 displayed a significant induction of tumor growth compared with xenografts transduced with vector, and the effects were reversed by RUNX1 knockdown." (PMID 36949071, 2023). "Although the expression levels of USP10, USP32, and USP33 were also significantly related to tumor differentiation to some extent, the result may be unreliable due to the small sample size." (PMID 36582601, 2022). "In order to investigate whether USP10 and HDAC7 signaling is specific for NSCLC tissues, we further analyzed the USP10 and HDAC7 co-expression by IHC staining in 71 paired tumor–normal tissue samples." (PMID 35277183, 2022). "USP10 may promote HCC proliferation on the one hand, yet on the other, it may function as a tumor suppressor." (PMID 36248971, 2022). "Meanwhile, tumor weight and volumes, but not the body weight of mice, in the USP10 inhibition group were also significantly reduced, compared with the vehicle group." (PMID 31044085, 2019). "Furthermore, USP10 can also interact with and deubiquitinate PTEN, USP10 inhibition stimulates tumor growth and invasion, but this effect can be abolished by reinserting PTEN." (PMID 30319415, 2018). "Finally, while 15 DUBs were found to be significantly dysregulated in only one type of cancer, 7 (UCHL1, USP9X, USP11, USP10, USP22, COPS5 and COPS6) displayed multiple alterations in two or more tumor types." (PMID 21283576, 2011). "Given that knockdown of USP10 reduced the expression of MRPS7 and MRPS23, and considering the lack of potent antagonists targeting MRPS7 and MRPS23 directly, we investigated spautin-1, a well-characterized USP10 inhibitor with demonstrated anti-tumor effects, as a potential therapeutic agent." (PMID 41522354, 2026). "USP10 and USP13 may act as a suppressor in BC by promoting autophagy in tumor cells." (PMID 40083330, 2025). "Our study revealed that the suppression of USP10 could decrease autophagy in PDAC cells and increase the chemotherapy sensitivity of GEM in vivo and in vitro, providing a potential pathway to enhance the anti-tumor activity of GEM." (PMID 40517136, 2025).
tumor (continued). "Besides, dysregulation in post-transcriptional modifications, like ubiquitination enzymes (HUWE1, CUL4A, TRIM25, etc.)and deubiquitination enzymes (USP7, USP10, USP24, etc.)in these PTC tumor samples may also lead to the low consistency." (PMID 38609408, 2024). "USP10 decreases ubiquitin-mediated degradation of YAP1 and further elevates cysteine-rich 61 (Cyr61), which then restores programmed cell death 1 ligand 1 (PD-L1) and galectin-9 expression and stimulates M2 polarization, thereby helping tumor cells evade from immune surveillance." (PMID 38174069, 2023). "Notably, the introduction of wild-type N1DARP, but not the N1DARP-20Y/34Y mutant, ameliorated USP10 overexpression-induced Notch signaling activation, as well as tumor stemness, chemoresistance, and progression." (PMID 37714834, 2023). "However, they noted that the anti-tumour function of spautin-1 in PCa is independent of USP10, USP13 and autophagy." (PMID 36564767, 2022). "Therefore, interactions between USP10, RNF168, and TOP2α may play a key role in the development of tumor resistance to TOP2 inhibitors." (PMID 36248971, 2022). "In short, USP10 cannot be simply defined as a tumor suppressor gene or an oncogene, and its function may be directly related to the function of its deubiquitinated gene, rather than USP10 itself having oncogenic or tumor suppressor effects." (PMID 36248971, 2022). "The result from GSE62165 and GSE21501 indicated that the expression levels of six-USPs were not related to tumor location (N = 118) and tumor size (N = 98), while GSE21501 data showed that USP10 and USP14 were robustly associated with lymphatic metastasis (N = 101)." (PMID 36582601, 2022). "Furthermore, the close association between USP10 expression and immune cell marker gene expression suggested that USP10 might function in PAAD and LIHC tumor immune regulation." (PMID 35433424, 2022). "Interestingly, we found comparable expression in PDAC tissues regardless of tumor stage, suggesting that the oncogenic functions of USP10 may be required early and through the course of disease progression." (PMID 36543867, 2022). "Prompted by this observation, we next studied USP10 and β-Catenin levels by Immunohistochemistry (IHC) of tissue micro arrays (TMA) of CRC patients comprising non-transformed and tumour tissue." (PMID 39443725, 2024). "USP10, β-Catenin and the oncogene MYC were increased in tumour-samples compared to matched non-transformed tissue samples." (PMID 39443725, 2024).
cancer (90 papers, 2011 to 2026). A tumor composed of atypical neoplastic, often pleomorphic cells that invade other tissues. "Results revealed a significant increase in apoptotic cell count in USP10 knockdown populations compared to controls, indicating that loss of USP10 sensitizes cancer cells to T‐cell mediated cytotoxicity." (PMID 39206932, 2024). "The correlation between the expression of USP10 and immune cell infiltration in various cancers prompted us to identify those cancers in which prognosis and immune infiltration were associated with USP10 expression." (PMID 35433424, 2022). "Given that USP10 expression was upregulated in a variety of cancers, we used ROC curves to assess the diagnostic value of USP10 for pan-cancer." (PMID 35433424, 2022). "In this review, we discuss recent studies that define the roles of USP10 in maintaining cellular function, its involvement in human pathologies, and the molecular mechanisms underlying its association with cancer and neurodegenerative diseases." (PMID 33277473, 2020). "USP10 has emerged as a central driver of oncogenesis across diverse malignancies, where it coordinates critical signaling cascades that regulate hallmark cancer processes, including uncontrolled proliferation, stemness maintenance, metastatic dissemination, and therapeutic resistance." (PMID 41522354, 2026). "Due to cancer cell ferroptosis is closely associated with chemotherapy or radiotherapy, patients with intact therapy and prognosis information in TCGA dataset were stratified to analyze the potential associations between USP10 and treatment modalities." (PMID 40605431, 2025). "USP10, an important member of the ubiquitin-specific protease family, is widely expressed in the cytoplasm and nucleus of almost all cells, and has been linked to anti-cancer activities." (PMID 38515149, 2024). "Importantly, we found that in different types of cancer, USP10 expression was associated with immune cell infiltration levels and has a critical function in cancer immunity, particularly in PAAD and LIHC." (PMID 35433424, 2022). "We postulated that USP10 expression might be linked to the TMB in various cancers to influence patient survival and is a useful immunotherapy biomarker for checkpoint blockade selection in many types of cancer." (PMID 35433424, 2022). "In patients with these cancers, high USP10 expression could be an independent risk factor." (PMID 35433424, 2022). "Moreover, USP10 mutations are closely associated with the development of cancers." (PMID 35433424, 2022). "We than investigated whether USP10 expression was linked to the prognosis of patients with cancer." (PMID 35433424, 2022). "Therefore, this study aimed to determine whether USP10 influences the prognosis of patients with cancer and if such an influence is associated with immune cell infiltration." (PMID 35433424, 2022). "Furthermore, USP10 is intimately linked to immune cell infiltration in certain cancers and might affect the overall survival of patients with PAAD and LIHC via immune infiltration." (PMID 35433424, 2022). "Ubiquitin-specific peptidase 10 (USP10) deubiquitinates multiple signaling proteins in cancer cells." (PMID 41892309, 2026). "Taken together, our data indicate that USP10 blocks cancer ferroptosis through the transcriptional activation of SLC7A11." (PMID 40605431, 2025). "The results suggested that the USP10 protein was upregulated in PDAC compared to that in tissues adjacent to cancer." (PMID 40517136, 2025).
cancer (continued). "Given that β-Catenin directly controls intestinal homeostasis and stem- and cancer cell maintenance, next, we tested if USP10 affects the expression of essential stem- and CRC pathways." (PMID 39443725, 2024). "Ubiquitin‐specific protease 10 (USP10) plays an important role in many biological processes and cancers." (PMID 39517125, 2024). "To investigate the potential role of USP10 in facilitating immune escape by cancer cells, we utilized a co‐culture system with cancer cells and human PBMCs, activating cytotoxic T‐cells with anti‐human CD3 and CD28.2 antibodies." (PMID 39206932, 2024). "Overall, we concluded that the use of Caprin1 and USP10-derived SIPs is an effective way to promote the efficacy of sorafenib treatment in cancer cells." (PMID 38731625, 2024). "Consistently, quantitative analysis of dendritic cell phagocytosis via flow cytometry confirmed a similar increase in phagocytosis of USP10 KD MDA‐MB‐468 cancer cells after SG treatment." (PMID 39206932, 2024). "A significant elevation in MHC‐I membrane expression was detected after coculturing with USP10 KD MDA‐MB‐468 cancer cells compared to controls." (PMID 39206932, 2024). "Real‐time live cell imaging revealed an increased percentage of dendritic cell phagocytosis of cancer cells in the coculture with USP10 KD cells." (PMID 39206932, 2024). "Purified human dendritic cells were cocultured with either control or USP10 knockdown MDA‐MB‐468 cancer cells pretreated with 100 ng mL−1 SG." (PMID 39206932, 2024). "Multiple deubiquitinating enzymes, including USP1, USP7, and USP10, have been reported to play a regulatory role in the development of various cancers." (PMID 37821462, 2023). "We also conducted wound healing and transwell migration assays to explore the effect of USP10 on the metastatic capacity of cancer cells." (PMID 37786443, 2023). "Studies have shown that abnormal USP10 expression is involved in epithelial-mesenchymal transition, cell migration, cancer, and immunity in thyroid tissue." (PMID 37919637, 2023). "In conclusion, we determined the universal applicability of USP10 in pan-cancer and found that high expression of USP10 is usually associated with poor clinical prognosis." (PMID 35433424, 2022). "Knockdown of NRAGE promoted PCNA K48-linked polyubiquitination, leading to proteasome-dependent degradation of PCNA and cancer proliferation inhibition, and USP10 is a key regulator in this process." (PMID 36248971, 2022). "In this study, we analyzed the differential expression of USP10 and its prognostic value in different types of cancer." (PMID 35433424, 2022). "The deubiquitination substrates and downstream signaling pathways of USP10 in different cancer types." (PMID 36248971, 2022). "Studies have shown that the abnormal expression of USP10 in different types of cancer correlates strongly with patient prognosis." (PMID 35433424, 2022). "Based on bioinformatics, this study investigated USP10 expression in pan-cancer and its correlation with prognosis and analyzed the importance of USP10 in the development of different cancers." (PMID 35433424, 2022). "We expect that the summary of such knowledge will help us to develop new inhibitors or strategies to target USP10 in human cancers in the future." (PMID 35627217, 2022). "In light of the important oncogenic role of USP10 in many cancers, inhibiting the expression or activity of USP10 is expected to be a promising therapeutic strategy for curing a range of human tumors." (PMID 35627217, 2022).
cancer (continued). "Comparatively, RFC2 has a high possibility of interacting with USP10 and belongs to the replication factor C family, which has been reported to promote cell invasion and migration of various cancers." (PMID 35791074, 2022). "We used immunofluorescence (IF) to examine the expression of USP10 protein in various cancer tissues and their normal counterparts." (PMID 35433424, 2022). "Kaplan–Meier survival analysis using the TCGA database demonstrated that in most cancer types (PAAD, LIHC, LUAD, and BRCA), high USP10 expression was associated with poor prognosis." (PMID 35433424, 2022). "This highlights that identifying more regulators of USP10 will be essential for clarifying the mechanisms and roles in different diseases, especially for cancer." (PMID 35627217, 2022). "In the Oncomine database, the levels of USP10 mRNA in various cancers and normal tissues were analyzed." (PMID 35433424, 2022). "In conclusion, USP10 plays a diverse set of roles in either promoting or inhibiting the progression of various of cancers." (PMID 36248971, 2022). "The transcriptional and translational levels of USP10 in these cancer types were broadly consistent." (PMID 35433424, 2022). "Herein, we focus on the involvement of USP10, along with its substrates and upstream regulators, in cancer cells." (PMID 35627217, 2022). "Although the aberrant expression of USP10 has been reported in many cancers, and the role of USP10 in tumorigenesis and prognosis has been partially confirmed in several cancers, a systematic bioinformatic analysis is still lacking." (PMID 35433424, 2022). "Several lines of evidence support the diverse roles of USP10 in tumorigenesis in different cancer types." (PMID 33838681, 2021). "Several lines of evidence have unraveled the diverse roles of USP10 in tumorigenesis as well as malignancy in different cancer types." (PMID 31721429, 2020). "The role of USP10 in cancer has remained elusive and complex, due to the diversity of its associated proteins and substrates." (PMID 32382008, 2020). "Rescuing HDAC6 or USP10 in USP10 knockdown cancer cells yielded a high survival rate and less PARP-1 cleavage." (PMID 32382008, 2020). "In the following section, the therapeutic potential of DUB inhibitors, especially inhibitors of USP10, will be discussed in a cancer-specific context." (PMID 33277473, 2020).